PIWIL1 (piwi like RNA-mediated gene silencing 1)
Diseases named in the same sentence as PIWIL1 in open-access papers (continued):
Sharing a sentence is not in itself a finding about the gene and the disease.
endometrial cancer (continued). "PIWIL1 is silenced in normal endometrium and is reactivated and carcinogenic in endometrial cancer." (PMID 38031146, 2023). "In addition, PIWIL1 mediated PTEN hypermethylation via DNA methyltransferase 1 in type I endometrial cancer." (PMID 36212439, 2022). "Another major mechanism by which PIWIL1 promotes endometrial cancer progression might be through the induction of DNA methylation at PTEN CpG islands." (PMID 33718392, 2021). "Our continued examination in this study indicates that estrogen could up-regulate the expression of PIWIL1 in ERα-positive endometrial cancer cells." (PMID 32503542, 2020). "Evidences showed that PIWIL1 as an oncogene was overexpressed in several tumors including gastric cancer, lung cancer, breast cancer, hepatocellular carcinoma, soft-tissue sarcoma, adenocarcinoma of the pancreas and endometrial cancer." (PMID 32503542, 2020). "These publications give clues about regulation of PIWIL1 by estrogen in endometrial cancer." (PMID 32503542, 2020). "The PIWIL1 promoter was hypomethylated in ERα-positive endometrial cancer cells." (PMID 32503542, 2020). "Our previous study revealed PIWIL1 as an oncogene in endometrial cancer." (PMID 32503542, 2020). "Variable levels of Piwil1 were detected across the endometrial cancer cell lines." (PMID 26506848, 2015). "Consistent with our RT-qPCR analysis, the protein expression of Piwil1 was also significantly higher in endometrial atypical hyperplasia (IS = 2.9, ***P < 0.001) and endometrial cancer tissues (IS = 5.0, ***P < 0.001) compared with normal endometrial tissues (IS = 1.5)." (PMID 26506848, 2015). "We observed that Piwil1 could downregulate epithelial marker E-cadherin and upregulate mesenchymal markers Vimentin and N-cadherin in endometrial cancer cells." (PMID 26506848, 2015). "Here, we showed that Piwil1 was highly expressed in human endometrial cancer." (PMID 26506848, 2015). "Our results suggest that Piwil1 may be a part of the molecular pathway necessary for activating the cell’s capacity for self-renewal in endometrial cancer." (PMID 26506848, 2015). "Therefore, the PIWIL1/DNMT1/PTEN signaling pathway may play a significant role in the progression of type I endometrial cancer." (PMID 35637965, 2022). "However, the relationship between DNA methylation status of PIWIL1 promoter and PIWIL1 expression in endometrial cancer is unknown." (PMID 32503542, 2020). "Therefore, it indicated that Piwil1 may represent a promising target for developing a novel treatment strategy for endometrial cancer." (PMID 26506848, 2015). "To evaluate the effect of Piwil1 in the acquisition of stem-like properties of endometrial cancer cells, we first studied whether the transfected cells created any shift in the patterns of expression of endometrial cancer stem cell markers, such as CD133, CD44 and ALDH1." (PMID 26506848, 2015). "Thus, Piwil1 may represent a promising target for developing a novel treatment strategy for endometrial cancer." (PMID 26506848, 2015). "Therefore, we for the first time reported that Piwil1 may regulate stemness of endometrial cancer cells." (PMID 26506848, 2015). "However, the exact function and mechanism of Piwil1 in endometrial cancer remains unclear." (PMID 26506848, 2015). "Our results suggested that stem cell protein Piwil1 play important roles in regulating EMT and the acquisition of stem-like properties of endometrial cancer cells." (PMID 26506848, 2015). "For example, estrogen induces the binding of ERα to the promoter region of piwi-like RNA-mediated gene silencing 1 (PIWIL1), a critical gene for stem cell self-renewal, leading to the overexpression of PIWIL1 in endometrial cancer cells and stimulating cancer cell proliferation." (PMID 33014829, 2020). "The mean scores for PIWIL1 staining were 10.32 for ERα-positive endometrial cancer samples and 1.82 for ERα-negative endometrial cancer samples." (PMID 32503542, 2020).
endometrial cancer (continued). "Indeed, PIWIL1 protein has been reported to play a role in modulating EMT and the promotion of endometrial cancer stem cells." (PMID 28423657, 2017). "In summary, to the best of our knowledge, we are the first to provide evidence that Piwil1 could induce EMT and endow endometrial cancer cells with stem-like properties." (PMID 26506848, 2015). "Piwil1 immunostaining was absent or weak in normal endometrial tissues but moderate-to-strong in endometrial atypical hyperplasia and endometrial cancer tissues." (PMID 26506848, 2015). "We observed a striking pattern of Piwil1 overexpression in endometrial cancer tissues compared to normal endometrial tissues (**P < 0.01)." (PMID 26506848, 2015). "However, our results also found that estrogen showed the function of down-regulation of PIWIL1 expression in ERα-negative endometrial cancer cell line." (PMID 32503542, 2020). "However, reports focusing on effect of Piwil1 in tumor biology are limited, and the correlation between Piwil1 and endometrial cancer progression is not well documented." (PMID 26506848, 2015). "Though these results are not sufficient to definitively designate Piwil1 as a prognostic factor for endometrial cancer, our expression data combined with our functional data suggest that Piwil1 might serve as a target for anticancer therapy." (PMID 26506848, 2015).
hepatocellular carcinoma (16 papers, 2015 to 2026). A malignant tumor that arises from hepatocytes. "Although some works in breast cancer, hepatocellular carcinoma and non-small cell lung cancer showed that upregulation in PIWIL1 expression is associated with metastasis and/or poor survival, discrepant data have been published." (PMID 38303021, 2024). "Overexpression of PIWIL1 is common to several tumor types (e.g., hepatocellular carcinoma (HCC)), and its aberrant expression has been associated with tumorigenesis and poor prognosis." (PMID 40301858, 2025). "Patients with high PIWIL1 had larger tumors, higher incidence of intrahepatic and lymph node metastasis and lower DFS and OS showing that PIWIL1 is an independent prognostic factor in hepatocellular carcinoma." (PMID 38303021, 2024). "In hepatocellular carcinoma, Piwi Like RNA-Mediated Gene Silencing 1 (PIWIL1) increases fatty acid metabolism via mitochondrial fatty acid β-oxidation (FAO) to accelerate energy production for rapid tumor growth." (PMID 38609997, 2024). "Overexpression of PIWIL1 in hepatocellular carcinoma cells significantly increases the intracellular ATP content to meet the needs of rapid cell proliferation." (PMID 38031146, 2023). "Reports have shown that PIWIL1 downregulation significantly reduced the proliferation, migration, and invasiveness of hepatocellular carcinoma (HCC)." (PMID 36212439, 2022). "Herein, we reported the novel of tumor cell-expressed Piwi Like RNA-Mediated Gene Silencing 1 (PIWIL1) in mediating the crosstalk of fatty acid metabolism and immune response of human hepatocellular carcinoma (HCC)." (PMID 33633112, 2021). "Similarly, three studies in hepatocellular carcinoma described increased levels of PIWIL1 in tumor specimens compared to peritumoral tissues." (PMID 38303021, 2024). "C3 secretion induced by Piwi Like RNA-Mediated Gene Silencing 1 protein (PIWIL1) in human hepatocellular carcinoma (HCC) cells leads to the activation of p38 and MAPK signalling in MDSCs, which, in turn, triggers the expression of immunosuppressive cytokine IL-10 in these cells." (PMID 35860237, 2022). "Likewise, the upregulation of PIWIL1 was reported in Hepatocellular Carcinoma (HCC)." (PMID 39717847, 2024). "al. did not detect PIWIL1 mRNA in hepatocellular carcinoma tissues." (PMID 38303021, 2024).
breast carcinoma (14 papers, 2012 to 2024). "PIWIL1 was also shown to be responsible for the progression of breast cancer both in vivo and in vitro." (PMID 39596284, 2024). "Breast cancers that were negative for PIWIL1 expression were more likely to be classified as Luminal A subtypes, whereas breast cancers with a high expression of PIWIL1 were more often classified as Luminal B or Triple Negative subtypes." (PMID 36980876, 2023). "Among the PIWI family, the most studied cancers were colorectal cancer and breast cancer, and PIWIL1 is the most studied protein among the PIWI family." (PMID 38023199, 2023). "PIWIL1 overexpression was also detected in breast cancer, and interestingly, it was found that the levels at which the gene was expressed can be used to classify different breast cancer subtypes." (PMID 36980876, 2023). "Higher PIWIL1 mRNA expression is significantly correlated to worsen overall survival for patients with breast cancer, renal cell carcinoma, rectum adenocarcinoma and sarcoma." (PMID 33718392, 2021). "In breast cancer, PIWIL1 and PIWIL3 gene expressions were reported to be upregulated, whereas PIWIL2 and PIWIL4 were downregulated compared with normal breast tissue." (PMID 32987715, 2020). "We measured mRNA levels of PIWIL1-2-3-4 using quantitative RT–PCR assays, in a series of 526 unilateral invasive breast tumors and 14 normal breast tissues (adjacent to breast cancer or collected from cosmetic breast surgery specimen)." (PMID 33008024, 2020). "However, this study performed on six different types of breast cancer cell lines and the results showed that PIWIL1 expression level is significantly higher in four cancer cell line than in normal breast cell line." (PMID 32211149, 2020). "Both PIWIL1 mRNA and PIWI-like 1 protein overexpressions are reported in breast cancer." (PMID 32987715, 2020). "Two studies showed significantly higher levels of PIWIL1 in breast cancer compared to non-tumorous tissue and reported a positive association with tumor size, lymph node metastasis and histological grade and negative association with tumor-specific survival rate." (PMID 38303021, 2024).
colorectal cancer (14 papers, 2012 to 2025). A primary or metastatic malignant neoplasm that affects the colon or rectum. "Based on DNA methylation data, the expression of PIWIL1 in human colorectal cancers and cell lines is directly associated with the hypomethylation of 6 CpG sites in its promoter region, an event frequently linked to CTA re-expression in pathological conditions." (PMID 31694219, 2019). "Previous reports from our group have uncovered a role for PIWIL1 in controlling cell cycle progression in Colorectal Cancer (CRC)." (PMID 39188528, 2024). "In colorectal carcinoma, four independent studies reported increased levels of PIWIL1 at transcript and protein level in cancer tissue compared to non-tumorous tissue." (PMID 38303021, 2024). "For example, FALEC can promote colorectal cancer progression via regulating miR-2116-3p-targeted PIWIL1." (PMID 36915193, 2023). "PIWIL1 expression status has been proposed as a prognostic biomarker in many tumors, such as pancreatic cancer, colorectal cancer, and colonic adenoma and adenocarcinoma." (PMID 35464758, 2022). "For example, PIWIL1 is able to regulate OCT4, which is a factor associated to poor prognostic and metastasic disease in colorectal cancer." (PMID 31443431, 2019). "The relationships between PIWIL1 expression and clinicopathological features of colorectal cancer (CRC) patients were analyzed by us." (PMID 28634417, 2017). "PIWIL1 overexpression has since been detected in sarcomas, where it drives tumorogenesis via increased global DNA methylation, in colorectal cancer, where it plays a role as a prognostic marker, and in other tumors." (PMID 25742785, 2015). "On the tissue level, PIWIL1 expression was associated with a stem cell gene signature in non-small cell lung cancer, and expression of the stem cell markers POU5F1 (Oct3/4) and SOX2 and OLIG2 in colorectal cancer and glioblastoma, respectively." (PMID 38303021, 2024). "Given the current evidence, PIWIL1 could be a potential prognostic biomarker in some cancer types, such as colorectal carcinoma." (PMID 38303021, 2024). "Strikingly, PIWIL1 was not detectable in 10 out of 11 colorectal cancer tissues, despite three independent studies reporting positive staining in large proportion of the tumors." (PMID 38303021, 2024).
seminoma (14 papers, 2009 to 2023). A radiosensitive malignant germ cell tumor found in the testis (especially undescended), and extragonadal sites (anterior mediastinum and pineal gland). "First, PIWIL1 expression has been analysed in male germline cells, showing that mRNA levels of PIWIL1 was upregulated in the occurrence of seminomas, that is, a type of testicular germ cell tumors." (PMID 20146808, 2010). "Previous study observed the existence of promoter CpG island hypermethylation-associated silencing of PIWIL1 in primary seminoma and non-seminoma testicular tumors." (PMID 32503542, 2020). "The first report of PIWI expression in tumor tissue was in seminomas, where PIWIL1 was detected in the tumor but not in normal tissue." (PMID 25742785, 2015). "Downregulation of PIWIL1, PIWIL2, PIWIL4, and TDRD1 genes expression due to hypermethylation of their promoters was also observed in primary TGCTs (both seminomas and nonseminomas) in comparison to normal testicular tissues." (PMID 35204687, 2022). "Namely, we found that PIWIL1/2/4 and DDX4 are concertedly expressed in preneoplastic testis tissue adjacent to nonseminoma but are downregulated in those adjacent to seminoma." (PMID 26843623, 2016). "Moreover, expression of PIWIL1 and PIWIL2 was upregulated in seminomas, but not in non-seminoma tumours." (PMID 35204687, 2022). "Furthermore, expression of PIWIL1/2/4 and DNA methylation level of LINE-1 promoters were found to coincide with this pattern: higher in tissues adjacent to nonseminoma than seminoma." (PMID 26843623, 2016).
pancreatic cancer (11 papers, 2015 to 2024). "Given our previous results related to patient outcome, we wonder whether PIWIL1 or PIWIL2 would be associated to any of the four described molecular subtypes of pancreatic cancer." (PMID 31443431, 2019). "Inactivation of PIWIL1 in mouse models of pancreatic cancer leads to significant tumor shrinkage and a dramatic reduction in metastatic growth." (PMID 33718392, 2021). "Further analysis revealed that PIWIL1 and PIWIL2, at both mRNA and protein expression levels, correlated positively with factors associated to the progenitor molecular subtype of pancreatic cancer." (PMID 31443431, 2019). "Then, mRNA expression of the most significant factors associated with each molecular subtype of pancreatic cancer of 186 pancreatic cancer patients from a TGCA dataset was correlated with PIWIL1 or PIWIL2 mRNA expression levels." (PMID 31443431, 2019). "In pancreatic cancer, PIWIL1 promotes metastasis through interrupting cell–cell adhesion." (PMID 38023199, 2023). "Moreover, at mRNA and protein levels, the expression of PIWIL1 was found to be associated with progenitor molecular subtype of pancreatic cancer, indicating that in resectable pancreatic cancer, PIWIL1 can be considered as a potential prognostic marker." (PMID 37953273, 2023). "On the one hand, the expression of PIWIL1 did not associate to pancreatic cancer prognosis; thus, further research is needed to dissect the role of PIWIL1 in pancreatic cancer progression." (PMID 31443431, 2019). "PIWIL1 and PIWIL2 have been recently evaluated in pancreatic cancer, and elevated expression of PIWIL2 conferred longer survival to patients." (PMID 32357464, 2020). "This study shows the differential role of PIWIL1 and PIWIL2 in pancreatic cancer." (PMID 31443431, 2019). "Based on these findings, PIWIL1 and PIWIL2 expression may be considered a potential prognostic biomarker for resectable pancreatic cancer and may serve to guide subsequent adjuvant treatment decisions." (PMID 31443431, 2019). "Similarly to previously reported results, PIWIL1 protein expression does not have enough statistical power to be considered a prognostic biomarker, although it exhibited an association with male patients and a trend toward significance with pancreatic tumor origin." (PMID 31443431, 2019). "Interestingly, a paradoxical function of PIWIL1/HIWI has surfaced, where the upregulation of piR-017061, which binds with PIWIL1, inhibited the mRNA translation of Ephrin A5 (EFNA5), involved in regulating cell growth and proliferation in pancreatic cancer." (PMID 39717847, 2024). "In pancreatic cancer cells, piRNAs were not detectable although PIWIL1 was aberrantly expressed." (PMID 38303021, 2024). "Comprehensive functional and mechanistic studies showed that, even in the absence of piRNA loading, PIWIL1 could still promote pancreatic cancer metastasis by acting as a co-activator of the anaphase-promoting complex/cyclosome to degrade a critical cell adhesion-related protein, Pinin." (PMID 33718392, 2021). "In the present study, we evaluated PIWIL1, PIWIL2, PIWIL3 and PIWIL4 expression in pancreatic cancer-derived cell lines and in one non-tumor cell line as healthy control." (PMID 32357464, 2020).
Azoospermia (10 papers, 2017 to 2026). Absence of any measurable level of sperm,whereby spermatozoa cannot be observed even after centrifugation of the semen pellet. "In this context, the identification of the homozygous LoF variant in PIWIL1 also resolves the controversy regarding a previously proposed association of heterozygous missense variants in PIWIL1 with azoospermia, which we had already suspected to be erroneous." (PMID 39122675, 2024). "Mutations within the human PIWIL1 (HIWI) gene, the ortholog of Miwi, have been implicated in patients suffering from azoospermia." (PMID 38327666, 2024). "In all mammals examined to date, PIWIL1 is required for spermatogenesis, with PIWIL1 null spermatocytes arresting at the pachytene stage of meiosis, resulting in azoospermia." (PMID 37298298, 2023). "Several genes that were downregulated in the KO testis are known to be involved in spermatogenesis, for example deleted in azoospermia-like (Dazl), stimulated by retinoic acid gene 8 (Stra8) and Piwi-like protein 1 (Piwil1)." (PMID 28706261, 2017).